KIT (KIT proto-oncogene, receptor tyrosine kinase)
Diseases named in the same sentence as KIT in open-access papers (continued):
Sharing a sentence is not in itself a finding about the gene and the disease.
tumor (continued). "Tumor cells were negative with the wide-spectrum cytokeratin panel (HMW-CK, LMW-CK, CK8/18, CK7, CK20), and also negative for CD34, Myogenin, S100, CD117 (KIT), CD31, ALK1, and CD99." (PMID 39768800, 2024). "Immunohistochemical staining (IHC) was performed to determine lineage, however, tumor cells were negative for pan-keratin, p40, CDX2, HER2, S100, CD45, SOX10, CD34, synaptophysin, chromogranin A, myogenin, DOG1, KIT (CD117), CD30, and ALK." (PMID 38497146, 2024). "Taken together, our results suggested a negative feedback loop between KIT and ZSWIM4 in GISTs, where ZSWIM4 serves as a tumor suppressor in GISTs by inhibiting KIT signaling and BMAL1, a key component of the circadian clock pathway." (PMID 38951864, 2024). "This tumor shows positive immunohistochemical reactions for smooth muscle actin and desmin, and a negative reaction for KIT (CD117)." (PMID 38512393, 2024). "Third, because tumor size, metabolic tumor volume, or pathological characteristics, all of which are potential indicators that could influence ctDNA positivity in GIST, have not been evaluated, their impact on ctDNA positivity or KIT mutational status could not be assessed in this study." (PMID 39516322, 2024). "Next, we characterised populations of SPG isolated from adult WT and Inha KO ‘normal’ testes (without visible tumours) by intracellular staining for PLZF, KIT and EOMES by flow cytometry." (PMID 37564373, 2023). "Considering that it is KIT but not IL-7R that was an independent prognostic factor, we suspected that leukemic cells with KITD816/D820 modified tumor microenvironment through affecting the profile of T cells." (PMID 35874754, 2022). "The tumor sample from one pazopanib‐responsive patient had alterations in FGFR1, KIT, and KDR, while the other had no alterations in genes associated with pazopanib activity." (PMID 34269527, 2021). "Immunohistochemistry demonstrated the tumor cells were focally positive for α-SMA, and negative for desmin, CD34, and KIT (CD117)." (PMID 33172434, 2020). "A single GIST biopsy sample P5 with undetectable expression of CK2 was deemed uninformative, due to lack of expression of KIT, p-KIT and CDC37, which suggest low tumour content." (PMID 31776458, 2020). "The fact that some patients had primary tumor surgery more then 6 months before treatment start also did not have any significant impact on the observed changes on CEC, CEP, KIT+ CD11b+ cells and M2 markers (data not show)." (PMID 26840567, 2016). "Cytoplasmic staining for KIT and the absence of other GIST markers, including DOG1 and platelet-derived growth factor α, indicated that the tumor was not a GIST." (PMID 24938355, 2014). "The level of CD117 expression on cytokeratin+/CD117+ cells was statistically indistinguishable between NL, KIT “negative” tumor and MPE." (PMID 23285214, 2012). "Immunohistochemically, the tumor cells were positive for KIT, negative for CD34, and negative or weakly positive for SMA, and the same result was observed for the highly aggressive tumor cells of the primary gastric lesion." (PMID 23227375, 2012). "The subdivision of tumors into 5 sub-branches shows a non-random distribution of tumor subtypes and immunohistochemical staining of KRT5/6, EGFR and KIT." (PMID 17910759, 2007). "Characteristics of the patients, such as gender, age, location of the tumor, TNM stage and cancer cell differentiation, were not significantly different between the KIT-positive and KIT-negative groups." (PMID 17044945, 2006). "No KIT, CD10, CA9, GATA3 or alpha-methylacyl-CoA racemase was detected in the tumor cells." (PMID 39980061, 2025). "Unlike TKIs that inhibit KIT phosphorylation by binding to ATP, KIT-d-MMAE binds to the extracellular domain of KIT and is internalized into the cell, leading to drug release and tumor cell apoptosis." (PMID 40963922, 2025). "Since c-KIT−/low cells can give rise to c-KIThigh cells and vice versa, targeting c-KIT may not be sufficient to effectively eradicate the tumor." (PMID 26682270, 2015).
tumor (continued). "The tumor was positive for α-smooth muscle actin and vimentin but negative for CD34 and KIT." (PMID 26697255, 2015). "This tumor had amplification of PDGFRA and KIT in region A not detected within other regions." (PMID 25608559, 2014). "The requirement of KIT+ tumor cells for dTc proliferation was confirmed by the minimal proliferation that resulted when culturing dTc in the presence of KIT- GIST 48B cells, and CIR- activated T cells did not proliferate in the presence of KIT+ tumor (data not shown)." (PMID 23433424, 2013). "In contrast, KIT protein immunoreactivity as assessed by IHC was found in only 8/24 primary and 3/10 LN AGASACA samples and 9/15 of the TC samples, with expression being localized to tumor cells, not stroma." (PMID 22630170, 2012). "Interestingly, IF analyses, as well as ChIP assays, fully recapitulated what was previously observed in BJ‐EHLT cells, indicating that the ability of KHSRP to bind the G4 structures located within the promoter regions of c‐KIT and c‐MYC is a generalizable phenomenon, independent of tumor histotype." (PMID 39763191, 2025). "Therefore, KIT positivity alone might not be adequate to diagnose a GIST, especially if the tumor is in the urinary bladder." (PMID 24938355, 2014). "Interestingly, impairment of cell proliferation in 2D and 3D by TCOF1 knockout could not be rescued by KIT overexpression, indicating that another downstream effector is responsible for mediating TCOF1’s function in cell proliferation and/or survival of bulk tumour cells." (PMID 34718356, 2022).
cancer (791 papers, 2004 to 2026). A tumor composed of atypical neoplastic, often pleomorphic cells that invade other tissues. "Rather, as mentioned for canines (Section 4.2.3), KIT is routinely assessed by the IHC as a diagnostic marker to distinguish between different cancer types." (PMID 38787171, 2024). "Since mutated cancer genes are often overexpressed, we evaluated the feasibility and sensitivity of KIT p.D816V detection by analysing mRNA/cDNA instead of genomic DNA." (PMID 39537990, 2024). "Some targeted drugs, such as imatinib, sunitinib and regorafenib, block cancer cell proliferation and survival by inhibiting aberrant signal activation mediated by KIT or PDGFRA mutations." (PMID 39070147, 2024). "The majority of KIT alterations found in cancer are associated with gain of function mutations leading to a constitutive activation of KIT independently from SCF." (PMID 39456668, 2024). "KIT gene mutations are common targets for the treatment of various cancers because of the gene’s role in cellular functions such as hematopoiesis, carcinogenesis, and melanogenesis." (PMID 37513844, 2023). "Accumulating evidence suggests that dysregulated c-KIT function, caused by either overexpression or mutations in c-kit, promotes tumor development and progression in various human cancers." (PMID 35490363, 2022). "Deregulation of RTK KIT, including overexpression and gain of function mutations, has been detected in several human cancers." (PMID 36361689, 2022). "The proto-oncogene KIT, which is associated with a large number of human cancers, has previously been found to contain three adjacent G4s, containing three, two, and three G-tetrads, respectively." (PMID 36555662, 2022). "This KIT variant corresponds to the N822K mutation found in human cancers, which is associated with imatinib-resistance." (PMID 36396684, 2022). "Mutations in the KIT gene were more likely found in brain metastases from both of these primary cancers." (PMID 35681762, 2022). "The KIT mutation plays a central role in various malignant tumors such as GIST and SM, and it is attracting attention as an important molecular target." (PMID 35563085, 2022). "Gene set enrichment analyses using 50 cancer hallmark signatures revealed a surprisingly concordant effect of altering KIT expression in these two completely distinct PDO models." (PMID 35842424, 2022). "The toxic effect of this RNase toward cancer cells is due to expression of specific oncogenes, e.g., KIT, RAS, AML1/ETO, and FLT3.1, whose mutations lead to activation of signaling pathways in various cancer cells and their uncontrolled proliferation." (PMID 35746037, 2022). "On the other hand, cancers that lack KIT or PDGFRA mutations (“wild-type” GISTs) are often unresponsive to such therapy." (PMID 36090331, 2022). "Mutations in c-KIT can either activate or deactivate the receptor, causing varying downstream functional consequences in different cancers." (PMID 33807778, 2021). "Self-sufficiency of growth signals and constitutive activation of mitogenic pathways is a hallmark of cancer, and malignant tumours often show deregulation of tyrosine kinases that include growth factor receptors such as KIT, EGFR, PDGFR, and VEGFR." (PMID 34822659, 2021). "KIT overexpression was associated with cancer stem cell-like subpopulations, driving progression and therapeutic resistance in several cancer types." (PMID 34639089, 2021). "We next explored the additional mutations associated with ASM development in our patient as ASM cells often carry mutations in cancer-related genes in addition to KIT." (PMID 33246418, 2020). "Based on NetworkAnalyst results and the matching of data based on KEGG datasets associated with pathways in cancers, KIT was identified, which is also a stem cell factor." (PMID 31619200, 2019). "And we found that one TF, E2F3 was related to ESCA, two genes, DTNA and KCNMA1 were related to STAD, while one TF ESR1 and one gene KIT were associated with both of the two types of cancer." (PMID 31888440, 2019).
cancer (continued). "These genes encode for proteins with well-known roles in cancer progression and normal stem cell maintenance (KIT), angiogenesis (SERPINE), and epithelial-mesenchymal transition (TWIST1, TWIST2, and ZEB2)." (PMID 31013771, 2019). "Although bosutinib’s action is not entirely isolated to Src inhibition, it is more selective than similar agents such as dasatinib which also target a range of cancer-implicated enzymes such as c-KIT." (PMID 31546727, 2019). "The stem cell factor c-KIT, encodes a receptor tyrosine kinase; involved in self-renewal and therapeutic resistance in many cancers including breast." (PMID 29796188, 2018). "For example, KIT is associated with various pathways related to cancer, such as pathways in cancer and PI3K-Akt signaling pathway." (PMID 28044124, 2016). "KIT mutations occur in benign entities such as mastocytosis as well as malignant tumors such as GIST." (PMID 27509178, 2016). "The exact role of targeted drugs for some of the cancer mutations reported by OncoFOCUSTM+KIT is unclear." (PMID 28163892, 2016). "To clarify the molecular features required by a G4-ligand (a) to bind the selected KIT1 and KIT2 sequences and, (b) to consequently cause the downregulation of c-KIT expression in cancer cells we started with the screening of a library of compounds." (PMID 26942875, 2016). "Checking all mutations affecting proteins against the latest ClinVar database yielded 48 single-nucleotide variants that have been linked to cancer or other diseases, of which the KIT mutation is the only somatic one." (PMID 26102504, 2015). "Resistance to the cancer therapeutics cisplatin and 5-fluorouracil has been linked to induced miR-148a expression and targeting of the gene KIT." (PMID 24926315, 2014). "Studies in mice suggest that the KIT D816V allele is a driver mutation in these cancers since expression of KITD816V, or the analogous mutation in mice (KITD814V), within hematopoietic stem cells (HSCs) leads to myeloproliferative disease (MPD) in mice." (PMID 25026279, 2014). "D816V-mutated KIT is constitutively active, and resistant to treatment with the anti-cancer drug Imatinib." (PMID 21698178, 2011). "Of special interest is a spectrum of EGFR, ABL, MET, FLT3 and KIT cancer mutations that correspond to the same structurally conserved position in the activation loop, which appeared to be mutated in at least 8 different kinases." (PMID 19834613, 2009). "Furthermore, it showed that only patients with FAT1 variants had CRC, and most patients harboured variants in genes such as CHEK2, ERBB2, and KIT in most of the cancers." (PMID 40627234, 2025). "GISTs and other cancers expressing un-mutated, wild-type KIT-RTKs, as well as those possessing exon 11, exon 9, and other less common activating mutations, can be inhibited with the KIT proto-oncogene receptor tyrosine kinases (KIT-TKIs) imatinib and ripretinib." (PMID 36734129, 2023). "In the era of biomarker-driven personalized cancer therapy, several biomarkers have been proposed as prognostic and predictive factors in different cancers, such as KIT mutations in gastrointestinal stromal tumors, EGFR mutations in lung cancer, and HER2 overexpression in breast cancer." (PMID 36979671, 2023). "We then illustrate how different c-kit alterations are associated with specific human cancers and describe recent studies that highlight the contribution of c-KIT to cancer stemness, epithelial-mesenchymal transition and progression to metastatic disease in different experimental models." (PMID 35490363, 2022). "Several mutations in c-KIT have been associated with the development of cancers." (PMID 35681762, 2022). "However, later studies showed a strong association of KIT with cancer stem cells, stage 4, and MYCN-amplified tumors, and our data strongly support these findings." (PMID 35887076, 2022). "Two carcinomas harboured a missense mutation in FGFR3 or KIT (p.L576P, p.Y823S)." (PMID 35884448, 2022).
cancer (continued). "The mutational profile of KIT in various cancer types is another issue." (PMID 31848942, 2020). "Cancer cells may adopt various strategies, such as amplified KIT signaling, increased EGFR phosphorylation, KRAS mutations oncogene, or increased NRG1 for activating HER2/3 kinases to survive crizotinib treatments." (PMID 32164629, 2020). "However, involvement of exon 13 and 17 of KIT in mutational changes is also frequent in various cancer types." (PMID 31848942, 2020). "Many of these lesions harbor KIT mutations identical to those identified in larger malignant lesions, indicating that additional genetic events are necessary to transform these micro-GISTs into malignant tumors." (PMID 30867899, 2019). "In our sequencing studies, solely 17.2% of GISTs harbored non-synonymous missense HSD11B1 mutations, and this low prevalence indicated their role as secondary aberrations in the cancer hallmark of metabolic deregulation among the GISTs that mostly manifested mutated-KIT or -PDGFRA." (PMID 30388854, 2018). "In our series two carcinomas with KIT mutations that predict sensitivity to imatinib were present." (PMID 27844328, 2017). "KIT is encoded by the protooncogene c-KIT, dysregulation of which occurs in many human cancers." (PMID 23738139, 2013). "Similarities with histological picture of gastrointestinal leiomyosarcoma, leiomyoblastoma and poorly differentiated carcinomas may cause diagnostic dielemma, Immuno-histochemical assays for CD117 antigen (KIT) is the mainstay for diagnosis." (PMID 23194007, 2012). "Imatinib mesylate reduces GIST cell proliferation by binding to the catalytic pocket of the KIT protein product, and serves as a hallmark representative for the emerging generation of cancer drugs that selectively inhibits the activity of cancer causing genes or their protein products." (PMID 17519908, 2007). "Thus, new treatment agents targeting cancers with KIT mutations are needed." (PMID 35563085, 2022). "That, all models using DLK2 and KIT had positive coefficients for their expression values (indicating increased expression of the markers is associated with increased BC risk) is consistent with their generally accepted roles in cancer development and progression." (PMID 28798985, 2017). "Consistently, the expression of CDKN1C and KIT was lower in cancers, including KIRC, KIRP, and BRCA, while ICAM1, SSX2IP, and TNFSF10 were higher in cancers, including STAD and CESC, opposing the effects of miR-221/222-3p." (PMID 41602427, 2026). "The results showed that low expression of KIT had an adverse effect on the survival of cancer patients, which was contrary to the effects of miR-221/222-3p in BRCA and KIRC." (PMID 41602427, 2026). "Among NB cell lines, a relatively low percentage of cells express KIT (5–20%), but KIT expression increases significantly under hypoxia conditions, and KIT is primarily expressed on surface of cancer stem cells." (PMID 41511287, 2025). "In the past decade, scientists and clinicians have noticed the potential of KIT as a therapeutic target in cancer." (PMID 39744440, 2025). "The Asp at position 7 is the Aspβ9 (FLT3 D835, KIT D816, and PDGFRA D842) which is recurrently mutated in many cancer types." (PMID 40831936, 2025). "It targets and inhibits specific tyrosine kinases, such as BCR-ABL in CML and c-KIT in GISTs, which are crucial for cancer cell proliferation." (PMID 40443612, 2025). "In contrast, KIT D816V, FLT3 D835Y, and PDGFRA D842V are activation loop mutations commonly found in acute leukemias, gastrointestinal stromal tumors, and other cancer types." (PMID 40831936, 2025). "Highly expressed genes were previously shown to be prime targets of HDAC inhibitors in (cancer) cell lines, including KIT in transformed human mast cells, in line with our own findings." (PMID 40498295, 2025). "Artemisinin is a multi-target drug that not only regulates the c-KIT pathway, but also the complex regulatory network in cancer." (PMID 41160271, 2025).